WAKMAR2 (wound and keratinocyte migration associated lncRNA 2)
Synonyms: lnc-TNFAIP3
Gene: Long non-coding RNA gene on chromosome 6 (137,820,625 to 137,868,233, reverse strand). Ensembl gene ENSG00000237499.
Diseases named in the same sentence as WAKMAR2 in open-access papers:
WAKMAR2 is named in the same sentence as 11 diseases in open-access papers, as found by Europe PMC text mining. Sharing a sentence is not in itself a finding about the gene and the disease. The quoted sentences say what the papers report.
breast carcinoma (3 papers, 2021 to 2022). "This study approved WAKMAR2 as a promising molecular marker for the prognosis of individuals with invasive breast cancer and provided indication for novel probable targets for breast cancer therapy." (PMID 36287118, 2022). "According to the finding, WAKMAR2 was acknowledged as a main candidate engaged in invasive breast cancer through modulating the tumor microenvironment and will possibly function by regulating immune-related target genes, including IL27RA, RAC2, FABP7, IGLV1-51, IGHA1, and IGHD." (PMID 36287118, 2022).
invasive breast carcinoma (3 papers, 2021 to 2022). A carcinoma that infiltrates the breast parenchyma. "In invasive breast cancer, the eRNA WAKMAR2 targets genes are involved in several crucial pathways, including cytokine activity, MHC class II protein complexes, and immunoglobulin-mediated immune responses." (PMID 35454885, 2022). "WAKMAR2 has a positive prognostic value in invasive breast cancer patients, likely due to the relatively high expression of its immune target genes." (PMID 35454885, 2022). "WAKMAR2 was demonstrated to be involved in tumor immunity and revealed decreased levels in invasive breast cancer specimens." (PMID 36287118, 2022). "Molecular biological methods were used to determine the expression of WAKMAR2 in patients with invasive breast cancer (IBC)." (PMID 34321580, 2021).
esophageal cancer (1 paper, 2021). A primary or metastatic malignant neoplasm involving the esophagus. "RP11-356I2.4 (also known as WAKMAR2, lnc-TNFAIP3, or LOC100130476) has been shown to act as a tumor suppressor gene in esophageal cancer and gastric cardia adenocarcinoma." (PMID 34367239, 2021).
glioma (1 paper, 2024). A benign or malignant brain and spinal cord tumor that arises from glial cells (astrocytes, oligodendrocytes, ependymal cells). "The Lasso analysis revealed that the expression of LINC01426, AC061992.2, CARD8-AS1, AC083855.2, AC027307.2, AC026356.1, LYRM4-AS1, WAKMAR2, and LINC02636 were associated with adverse survival time and DSS in patients with glioma." (PMID 38460946, 2024). "We further found that the expression of SUMF1, LINC01426, AC061992.2, CARD8-AS1, AC083855.2, AC027307.2, WAKMAR2, and LINC02636, were associated with adverse progression in patients with glioma." (PMID 38460946, 2024). "Additionally, the expression of LINC01426, AC061992.2, CARD8-AS1, AC083855.2, AC027307.2, WAKMAR2, LINC02636, and SUMF1 were correlated with adverse PFI in patients with glioma." (PMID 38460946, 2024).
mesothelioma (1 paper, 2021). A usually malignant and aggressive neoplasm of the mesothelium which is often associated with exposure to asbestos. "Kaplan–Meier survival analysis of pan-cancer results showed that patients with higher WAKMAR2 expression in adrenocortical carcinoma (ACC), brain lower grade glioma (LGG), and mesothelioma (MESO) had a markedly shorter overall survival than those with low WAKMAR2 expression." (PMID 34321580, 2021).
tumor (5 papers, 2021 to 2022). "In this study, we observed that the target immune genes of WAKMAR2 were highly expressed in a variety of tumours." (PMID 34321580, 2021). "Compared with that in para-carcinoma tissue, the expression of WAKMAR2 in tumour tissue was significantly reduced." (PMID 34321580, 2021). "Gene silencing and overexpression studies demonstrated that WAKMAR2 was a negative regulator of tumor-like phenotypes of RA FLS." (PMID 33664742, 2021). "Further enrichment analysis revealed that the eRNA WAKMAR2 may play a crucial role in tumour immunity." (PMID 34321580, 2021). "WAKMAR2 was found to be highly involved in tumour immunity and was downregulated in IBC tissues." (PMID 34321580, 2021). "Our further research suggested that WAKMAR2 is crucial in regulating the tumour microenvironment and may function by regulating immune-related genes, including IL27RA, RAC2, FABP7, IGLV1-51, IGHA1, and IGHD." (PMID 34321580, 2021). "Here, we identified WAKMAR2 as a crucial eRNA in the IBC tumour immune system." (PMID 34321580, 2021).
cancer (1 paper, 2021). A tumor composed of atypical neoplastic, often pleomorphic cells that invade other tissues. "Furthermore, the expression of WAKMAR2 and its target genes was observed at the pan-cancer level." (PMID 34321580, 2021).
WAKMAR2 also shares sentences with these, for which no sentence is quoted: gastric cardia adenocarcinoma (1 paper); pancreatic adenocarcinoma (1); pheochromocytoma-paraganglioma (1); stomach adenocarcinoma (1).